SIRPA (signal regulatory protein alpha)
Diseases named in the same sentence as SIRPA in open-access papers (continued):
Sharing a sentence is not in itself a finding about the gene and the disease.
tumor (continued). "SIRPα is not expressed in normal astrocytes but exhibits functional expression in astrocytomas, potentially participating in cell adhesion and signaling through CD47-dependent phosphorylation and SHP-2 recruitment, thereby influencing tumor invasiveness." (PMID 40589735, 2025). "Extracellular vesicles, including exosomes, released from CD47-overexpressing normal or tumor cells (transgenic or native), can induce efficient CD47 cross-dressing on pig or human cells, which can interact with SIRPα to inhibit phagocytosis without transmitting harmful cellular signals." (PMID 38426113, 2024). "This leads to a debate about CD47-SIRPα blocking agents that whether blocking the interaction between SIRPα and CD47 alone, independent of FcR activation, is sufficient to trigger macrophage phagocytosis and tumor cell elimination." (PMID 37691932, 2023). "However, macrophages do not phagocytose tumor cells because of high levels of CD47, a cluster of differentiation 47, in tumor cells, which inhibits phagocytosis vis interaction with SIRPα, signal regulatory protein α." (PMID 37686603, 2023). "Since the SIRPα/CD47 axis is a myeloid checkpoint, this could explain why IgA-stimulated neutrophils from NXG mice are not able to kill tumor cells properly." (PMID 37338671, 2023). "To evaluate whether the combination of HRT with anti-SIRPα could result in an abscopal effect on the nonirradiated tumors, we implanted MC38 tumor cells in both flanks of mice, and only the primary tumors (right flank) were irradiated." (PMID 37291116, 2023). "Indeed, SIRPα/CD47 pathway is referred to as the “do-not-eat-me” signal and tumor cells with CD47 expression can be recognized as self-normal cells and escape phagocytosis." (PMID 35493456, 2022). "In this study, we demonstrated that azelnidipine could dual target SIRPα and PVR, simultaneously block the negative signal pathway, enhance the phagocytosis of tumor cells by macrophages, and significantly inhibit tumor growth." (PMID 34068552, 2021). "Given that RT-activated Sirpα−/− macrophages robustly induce tumor-specific cytotoxic CD8 T cells, we further tested whether IR of primary lesions in Sirpα−/− mice could have an abscopal effect on nonirradiated tumors." (PMID 34050181, 2021). "Therefore, we suggested that tumor cells also would express SIRPα, although double staining for H3G34W and SIRPα was not possible in our study." (PMID 34285260, 2021). "However, in vitro killing of the tumor cells by NK cells was not inhibited by the same antibody, suggesting CD47 function in NK cells to be independent of SIRPα." (PMID 32117298, 2020). "Furthermore, they imply that the endogenous low affinity extracellular domain of SIRPα does not function as a robust CD47-targeting agent by itself and that the activity of licMABs is dominated by high affinity binding to the tumor antigen." (PMID 28061465, 2017). "Notably, this is almost an order of magnitude lower than the concentration typically used for CD47 blocking Abs and recombinant SiRPα-Fc proteins and likely explains the detection of T cell–secreted CV1-Fc but not wtSiRPα-Fc binding to CD47+ tumor cells from culture supernatants." (PMID 38828721, 2024). "Furthermore, previous studies have shown that CD47-lentiviruses are more effective in transducing SIRPα+ non-phagocytic tumor cells, suggesting that the interaction of CD47 with SIRPα may facilitate lentiviral engulfment by target cells." (PMID 36454036, 2022). "Surprisingly, both CD24 and CD47, two classic ligands of “don’t eat me” signal, were notably upregulated on tumor cells from mice received anti-CD20 antibody, whereas comparable expression levels of their receptors were observed on macrophages, Siglec-10 and SIRPα, respectively (Data not shown)." (PMID 36249034, 2022). "Therefore, direct targeting of SIRPα in immune cells, rather than CD47 in tumor cells, could be considered as an alternative approach to disrupt their interaction." (PMID 27671753, 2016).
tumor (continued). "It is plausible that both strepto-47VHH1H4B and B6H12.2 effectively outcompeted SIRPα in binding to the tumor receptor, which may explain why the difference in affinity between strepto-47VHH1H4B and B6H12.2 did not significantly alter the tumor growth dynamics." (PMID 38247566, 2024). "However, we cannot exclude the possibility that the secretion of a tumor-specific antigen may induce the expression of additional factors, which may induce the intrathymic negative selection in cooperation with CCR2-expressing Sirpα+ cDCs." (PMID 22815949, 2012).
cancer (457 papers, 2013 to 2026). A tumor composed of atypical neoplastic, often pleomorphic cells that invade other tissues. "In SIRPα-deficient mice, MY-1 monotherapy showed inhibition of cancer growth by binding to SIRPβ and promoting ADCP." (PMID 40589735, 2025). "In contrast, high SIRPα expression by CD68+ TAMs (SIRPα/CD68-ratio) was linked with CD47 expression by cancer cells, low TIL-score, and poor prognosis (p = 0.02)." (PMID 35406573, 2022). "High expression, however, of SIRPα by CD68+ TAMs was linked with CD47 expression by cancer cells, low TIL-score, and poor prognosis." (PMID 35406573, 2022). "Supporting the role of Sirpα-deficient macrophages in activating cancer-specific Tc to eliminate tumors, Sirpα-deficient macrophages plus local IR also induce abscopal remission of smaller tumors (<100 mm3)." (PMID 34050181, 2021). "This interaction causes SIRPα phosphorylation to deliver a potent “don’t eat me signal,” blocking phagocytosis of cancer cells." (PMID 33422072, 2021). "A typical scenario would see CD47 (“don’t eat me” signal) expressed on a cancer cell bind to SIRPα on an immune effector (e.g. macrophage) causing an inhibitory signal in the effector cell which dampens phagocytosis." (PMID 33552071, 2020). "The hNVs consist of P-NVs, M1-NVs, and cancer cell-derived NVs overexpressing high-affinity SIRPα variants (SαV-C-NVs)." (PMID 32999291, 2020). "For example, the binding domain of human SIRPα was modified to produce high-affinity variants, which demonstrated anti-cancer effects either as single agents or when combined with rituximab." (PMID 27863402, 2016). "CD7/SIRα is an important innate immune checkpoint in cancer, and one study found that high SIRPA expression was associated with a favorable response to anti-PD-1 therapy, which explains the downregulation of SIRPA in the high-risk group." (PMID 40149637, 2025). "However, here we demonstrate that the presence of Sirpα-deficient intratumoral macrophages can instead augment cancer therapies, including RT." (PMID 34050181, 2021). "Indeed, the augmented anti-cancer efficacy of RT conferred by Sirpα-deficient macrophages was unmatched by therapeutic combinations with anti-PD-L1 checkpoint inhibitors, CD47-blockade, and/or antitumor antibodies." (PMID 34050181, 2021). "Thus, we believe that blockade of the SIRPα/CD47 axis using a pan-allele SIRPα mAb provides a novel approach to immunotherapy that may be applicable for a broad range of cancers." (PMID 31801627, 2019). "Prior reports have identified high SIRPα expression as a marker of poor prognosis in several cancers." (PMID 40926176, 2026). "CD47/signal‐regulatory protein α (SIRPα) signaling enables malignant cells to evade macrophage‐mediated phagocytosis, offering a promising strategy for cancer therapy via immune checkpoint blockade." (PMID 41168993, 2026). "The cell surface protein CD47, a “don’t-eat-me” signal overexpressed on cancer cells and connected to worse prognosis, interacts with the signal regulatory protein alpha (SIRPα) on phagocytes to overpower pro-phagocytic “eat-me” signals and prevent engulfment." (PMID 41590379, 2026). "This review compares the structure, ligand interactions, and signaling mechanisms of SIRPα, SIRPβ, and SIRPγ, summarizes their roles in cancer, autoimmunity and neurodegeneration, and surveys therapeutic strategies that target the CD47-SIRPα axis." (PMID 41822520, 2026). "In summary, targeting the immune checkpoint receptor SIRPα can boost both innate and adaptive immune responses, offering novel strategies for cancer immunotherapy." (PMID 40589735, 2025). "A 2022 study from Texas MD Anderson Cancer Center highlighted the dual role of SIRPα in cancer treatment." (PMID 40356928, 2025). "As a transmembrane protein, CD47 interacts with signal regulatory protein alpha (SIRPα) on macrophages, thereby inhibiting phagocytosis and contributing to immune evasion—a mechanism that has garnered increasing interest in cancer research." (PMID 41163221, 2025).
cancer (continued). "Considering that CD47 is a marker that is highly expressed in cancer cells and interacts with SIRPα to prevent their own phagocytosis, this pathway can be inhibited through anti-CD47 or anti-SIRPα therapy leading to more phagocytosis of cancer cells." (PMID 41142789, 2025). "Despite the limited research on endogenous SIRPα in cancer cells, multiple pivotal studies have shed light on the role of endogenous SIRPα in the malignant progression of cancers." (PMID 40589735, 2025). "Increasing evidence demonstrates that blocking the interaction between CD47 and SIRPα can enhance cancer cell clearance by macrophages, which is particularly relevant in SCLC, where TAMs are the dominant cell type in the TME." (PMID 40361334, 2025). "The interaction between CD47, overexpressed on many cancer cells, and SIRPα on phagocytes delivers a “don’t eat me” signal, inhibiting phagocytosis and facilitating immune evasion." (PMID 40396172, 2025). "CD47 is a surface receptor on cancer cell and delivers the “don’t eat me” signal by interacting with SIRPα on myeloid cells, while costimulatory molecules CD80 and CD86 participate in the regulation of antigen presentation and T cell activation." (PMID 40708945, 2025). "As an immune checkpoint in the myeloid-specific system, CD47 effectively protects cancer cells from phagocytosis by binding to SIRPα on phagocytic cells, thereby inhibiting the phagocytic activity of macrophages in the immune system[33,]." (PMID 40129966, 2025). "It preventsphagocytosis by binding to signal regulatory protein alpha (SIRPα)on macrophages, helping cancer cells evade immune system clearance,prolonging their circulation." (PMID 40720603, 2025). "IBI397, a pan-allelic antibody against SIRPα, underwent clinical trials for advanced malignant tumors but the trial (NCT05245916) was withdrawn owing to changes in the company’s development strategy." (PMID 40589735, 2025). "We propose that F05 is a promising SIRPα specific agent with the potential for treatment in a variety of cancer types." (PMID 40408355, 2025). "CD47 is broadly expressed on normal cells but is frequently upregulated in cancer, including hematologic malignancies and solid tumors, where it engages signal regulatory protein alpha (SIRPα) on macrophages and dendritic cells (DCs)." (PMID 41179296, 2025). "CD47 inhibitors have emerged as promising candidates in cancer immunotherapy by activating macrophage phagocytosis through CD47/SIRPα signal blockade and enhancing dendritic cell antigen presentation." (PMID 40652522, 2025). "CD47, found on both healthy and malignant cells, regulates macrophage-mediated phagocytosis by sending a “don’t eat me” signal to the signal-regulatory protein alpha (SIRPα) receptor, being a popular target for clinical trials in cancer immunotherapy." (PMID 40361334, 2025). "This distinction makes SIRPα-targeting antibodies a potentially safer alternative in cancer immunotherapy." (PMID 40356928, 2025). "Targeting signal regulatory protein-α (SIRPα) or CD47 to restore the phagocytosis activity of TAM is another immunotherapeutic approach being used to treat different cancers." (PMID 41019045, 2025). "In cancer therapeutics, anti-SIRPα antibodies exert their antitumor effects by disrupting the CD47-SIRPα interaction and relieving inhibitory signaling on neutrophils)." (PMID 40589735, 2025). "CD47 is highly expressed on cancer cells and triggers an anti-phagocytic “don’t eat me” signal when bound by the inhibitory signal regulatory protein α (SIRPα) expressed on macrophages." (PMID 40078999, 2025). "Emerging research underscores the therapeutic potential of targeting the signal-regulatory protein alpha (SIRPα)-CD47 immune checkpoint in cancer treatment." (PMID 41402667, 2025).
cancer (continued). "Since the binding of CD47 on cancer cells to SIRPα on macrophage results in inhibition of macrophage phagocytosis, bioinformatic analysis using TISIDB database suggests that TRAF2 expression is negatively correlated with macrophage abundance in LUSC." (PMID 39665172, 2025). "The increased expression of CD47 on MHC-II+ cancer cells further promoted interactions with SIRPα on macrophages, to a greater extent than that observed in MHC-II− cancer cells." (PMID 41281745, 2025). "Emerging clinical trials are examining the effectiveness of anti-CD47 mAbs and SIRPα-Fc fusion proteins in various cancers." (PMID 41350707, 2025). "In the pre-clinical setting, several SIRPα targeting monoclonal antibodies have been efficacious in vivo in several cancer types." (PMID 40408355, 2025). "CD47 interaction with signal regulatory protein alpha (SIRPalpha) inhibits macrophage activation and protects cancer cells from phagocytosis and T cell activation." (PMID 40565299, 2025). "The active CD47/SIRPα signaling pathway drives evasion of immune surveillance in a variety of malignancies and therefore poses a greater challenge for cancer treatment, including PDAC." (PMID 41350707, 2025). "Several approaches to inhibit CD47/SIRPα signaling are currently being tested in cancer, either specifically blocking CD47 or SIRPα with antibody-based or gene knockout approaches, as well as bispecific approaches that block both CD47 and SIRPα." (PMID 40082557, 2025). "IMM0306, a fusion protein that combines CD20 mAb with the CD47-binding domain of SIRPα, activates both macrophages and NK cells, currently undergoing trials in a variety of cancer types." (PMID 40070841, 2025). "Strategies that combine immune checkpoint PD-1/PD-L1 blockade with innate immune checkpoint CD47/SIRPα blockade exhibit potential in cancer immunotherapy." (PMID 40296909, 2025). "CD47, a negative regulator of the macrophage scavenging receptor SIRPα, is often expressed on cancer cells, enabling evasion of cellular removal in certain cancers." (PMID 41007845, 2025). "Known as a “don't eat me” signal on cancer cells, ligation of signal regulatory protein alpha (SIRPα) on macrophages to CD47 prevents macrophage phagocytosis of cancer cells." (PMID 38646648, 2024). "The SIRPα/CD47 signaling axis has emerged as a promising therapeutic target in cancer immunotherapy." (PMID 39160226, 2024). "The identification of small molecules with dual-blocking effects on PD-1/PD-L1 and CD47/SIRPα interaction is crucial for cancer treatment." (PMID 38462636, 2024). "Treatments aimed at blocking the interaction between CD47 and SIRPα are the most advanced in clinical trials and are currently being explored in the clinic for various human cancers." (PMID 38881902, 2024). "CD47/SIRPα plays its part not only in cancer but also is crucial for red blood cell maintenance under physiological conditions." (PMID 38892394, 2024). "Cancer cells can evade immune surveillance via the immune checkpoint CD47/SIRPα, and blocking this immune checkpoint is a useful strategy to engineer macrophages for cancer immunotherapy." (PMID 38383737, 2024). "The availability of clinically relevant humanized anti-SIRPA antibodies has made the proposed therapeutic approach feasible since all three antibodies are already in use in clinics to treat cancer patients." (PMID 38920727, 2024). "CD47 is a cell surface protein expressed on cancer cells that interacts with SIRPα on macrophages, delivering a “don’t eat me” signal and inhibiting phagocytosis." (PMID 39040441, 2024). "The CD47/SIRPα axis is an innate IC that regulates phagocytosis of cancer cells by macrophages and other myeloid cells and is thus exploited by tumors to escape innate immunity." (PMID 38414061, 2024). "The feasibility of using anti-CD47 and -SIRPα blocking antibodies for the treatment of various cancers is currently being evaluated in phase I/II clinical trials." (PMID 39039207, 2024).